SMN2-AS1 (SMN2 antisense RNA 1)
Synonyms: SMN-AS1
Gene: Long non-coding RNA gene on chromosome 5 (70,055,820 to 70,057,416, reverse strand). Ensembl gene ENSG00000285151.
Homologues: Paralogues in human: SMN1-AS1 (100% identical).